RNU11-3P (RNA, U11 small nuclear 3, pseudogene)
Gene: Small nuclear RNA gene on chromosome 10 (103,312,436 to 103,312,568, reverse strand). Ensembl gene ENSG00000212413.
Homologues: Orthologues: chimpanzee RNU11-3P (100% identical), rat LOC120093427 (87% identical), rat LOC120094898 (86% identical), rat LOC120095432 (86% identical), rat LOC120102644 (86% identical), rat LOC120099466 (85% identical), rat LOC120097590 (83% identical). Paralogues in human: RNU11-5P (67% identical).